STAT3 (signal transducer and activator of transcription 3)
Diseases named in the same sentence as STAT3 in open-access papers (continued):
Sharing a sentence is not in itself a finding about the gene and the disease.
tumor (continued). "Next, we looked into the average expression of SMG1, STAT3 and IL6ST only in tumor cells from each patient and we performed a correlation analysis for the expression or each factor with SMG1." (PMID 36443756, 2022). "A signal transducer and activator of transcription 3 (STAT3) promotes NPC oncogenesis through mechanisms within cancerous cells and their interactions with the tumor microenvironment, which is critical in the initiation, progression, and metastasis of NPC." (PMID 36313702, 2022). "Our data indicate that the combined inhibition of STAT3 and MEK induces ESCC cell senescence, which plays an anti-tumor role in nude mice." (PMID 35614034, 2022). "First, rNDV-VEGF-Trap inhibits the activation of AKT, ERK and STAT3 signaling pathways by blocking VEGF and VEGF receptor binding, leading to a reduced tumor angiogenesis." (PMID 35381011, 2022). "The results revealed that the INTERFERON_GAMMA_RESPONSE pathway, the IL2_STAT5_SIGNALING pathway, the TNFA SIGNALING VIA NKFB pathway, the UV_RESPONSE_UP, IL6_JAK_STAT3_SIGNALING pathway, and the HYPOXIA pathway were upregulated in tumor-infiltrating cells." (PMID 35812372, 2022). "In conclusion, the present study revealed the crucial role of LXN in tumor tumorigenesis from an immunological perspective, and its ability to regulate tumor microenvironment through modulating JAK1/STAT3/PD-L2 axis in macrophages." (PMID 36323670, 2022). "Alternatively, it has been observed that the signal transducer and activator of transcription 3 (STAT3) factor are overexpressed in several cancers, encouraging tumor formation and progression." (PMID 35684331, 2022). "We suggest that the STAT3/miR-130b-3p/MBNL1 feedback loop is critical for mTORC1-mediated angiogenesis and tumor growth, and that it can be targeted for the treatment of cancers associated with dysregulated mTORC1 activity." (PMID 36217202, 2022). "RNA-sequencing data from the Tumor, Normal and Metastatic (TNM) plot database showed a positive correlation between Smad7 and Stat3 in 1450 CRC samples." (PMID 36291778, 2022). "Overall, at least two molecular mechanism for tumor-supporting function of CD163+ TAMs were identified to date: inhibition of tumor suppressor TAp73 in breast cancer and activation of STAT3 signaling in TAMs and in r fibrosarcoma cells." (PMID 36686729, 2022). "In breast cancer, tumor-derived lactate can activate the ERK1/2 and its downstream STAT3 signaling to induce macrophage M2 polarization for tumor growth and angiogenesis." (PMID 36612084, 2022). "In mice, the activity of the combination was accompanied by disruption of the STAT3- DNMT1 complex formation and demethylation of several tumor-suppressor gene promoters." (PMID 35327559, 2022). "Many natural compounds affect tumor progression by suppressing activation of pathways involved in cell growth and proliferation, such as the JAK2/STAT3 pathway." (PMID 35116094, 2022). "ESC can inhibit the phosphorylation of STAT3 during macrophage differentiation, downregulate the production of VEGF and TGF-β1 in tumor cells and inhibit tumor growth." (PMID 36408214, 2022). "Among these DETs, multiple genes, including STAT3, PDGFA, PLD2, and PIK3R2, have been reported to be involved in tumor growth." (PMID 35291563, 2022). "Neutrophils have been shown to support tumor angiogenesis via the release of numerous pro-angiogenic factors, such as VEGF, FGF-2, oncostatin M, IL-17, MMP-9, Bv8, S100A8/9 alarmins, STAT3, and NETs." (PMID 35158807, 2022). "SOST interacted with STAT3 to enhance the TGF-β/KRAS signaling, increasing both tumor growth and bone metastasis." (PMID 36581888, 2022). "Among them, the activation of the STAT3 signaling pathway by IL-6 increases the number of CRC initiating cells, which can induce non-tumor stem cells to express stem cell markers and increase tumorigenic capacity in vivo." (PMID 35953863, 2022).
tumor (continued). "A growing body of evidence suggests a link between TLR4 and pSTAT3—more particularly, TLR4 signaling activates and cooperates with STAT3, to induce the formation of EMT-like CSCs and to promote tumor growth and immunosuppression." (PMID 35205801, 2022). "The group contains seven members, of which STAT3, STAT5, and STAT6 are involved in tumor progress, metastasis, and therapy resistance." (PMID 35207527, 2022). "STAT3 and EZH2 are potential molecular biomarkers for tumor progression and serve as poor predictors of outcomes." (PMID 35208478, 2022). "The Western blotting results showed that PPII lowered phospho-AKT, phospho-mTOR, phospho-STAT3, phospho-Src, and Bcl-XL and upregulated the LC3B-II protein level in tumor tissues." (PMID 36233191, 2022). "(I) Mean percentage of apoptotic B16F10, transfected with STAT3-T2A-iRFP670, EGR1-T2A-GFP or both, following incubation with tumor reactive T cells (n=3)." (PMID 36124553, 2022). "We demonstrate that genetic ablation of STAT3 in PDAC CAFs prolonged survival and reduced tumor progression in the KPF mouse model." (PMID 35803738, 2022). "Studies in which myeloid STAT3 is ablated show that the myeloid compartment shifts from STAT3- to STAT1-driven signaling, thereby skewing to an anti-tumor response." (PMID 35406557, 2022). "Here we report a first-in-class molecule, a novel, single domain camelid VHH antibody (15 kDa), SBT-100, that binds to both STAT3 and KRAS and can penetrate the tumor cell membrane, and significantly inhibit cancer cell growth." (PMID 35886918, 2022). "The activation of Stat3 induced the secretion of glutamic acid-leucine-arginine (ELR) motif CXCLs (CXCL1, CXCL2, CXCL3 and CXCL8) in tumor cells." (PMID 35280694, 2022). "Immunohistochemistry analysis for phospho-STAT3 (Tyr 705) and SHP-2 in subcutaneous tumor showed strong expression of SHP-2 and reciprocal decrease in phospho-STAT3 by ciglitazone." (PMID 36362294, 2022). "Meanwhile, drug resistance was observed for another commercial STAT3 inhibitor S3I201 in DU145 cells with an IC50 value of 1,014 μM and a similar effect as 323s to inhibit tumor cell proliferation in LNCaP cells." (PMID 35712699, 2022). "FGFs activate MAPK-ERK, JAK2/STAT3 and PI3K/AKT signalling pathways, which has been identified as key mediators in tumour progression promotion." (PMID 35864158, 2022). "Promotes STAT3 phosphorylation and binds AURKA, leading to Aurora A expression in drug‐resistant tumor cells, thereby promoting the expression of drug resistance." (PMID 37786890, 2022). "Exosomal LncRNA ZFAS1 also promotes the proliferation, migration and invasion of tumor cells from esophageal carcinoma (ESCC), and inhibits the apoptosis of ESCC cells by up-regulating STAT3 and down-regulating MiR-124, leading to the carcinogenesis of ESCC." (PMID 35359390, 2022). "On the contrary, hepatocyte-specific SHP2 knock-out leads to the development of HCC in mice by activating Stat3, suggesting that SHP2 can inhibit tumor growth." (PMID 35061863, 2022). "Some oncogenes have been identified, such as MYC, which regulates the anti-tumor immune response through CD47 and PD-L1, and ALK, which affect the expression of PD-L1 through STAT3 pathway." (PMID 36505487, 2022). "In the tumor microenvironment, IL6/JAK/STAT3/SIGNALING played an important role in promoting the proliferation and metastasis of tumor while strongly inhibiting the antitumor immune response." (PMID 34712264, 2021). "A recent study revealed that baicalin decreased STAT3 activity and further downregulated IFN-γ-induced PD-L1 expression to promote anti-tumor immunity." (PMID 33558586, 2021). "On the contrary, adiponectin can suppress tumor growth by either activating JNK-mediated mitochondrial apoptosis and caspases, or inhibiting Akt and STAT3." (PMID 33920670, 2021).
tumor (continued). "IL‐6 secreted by tumor cells can activate the signal transducers and activators of transcription 3 (STAT3)‐VEGF pathway of lymphatic endothelial cells and encourage lymphatic metastasis of the tumor." (PMID 34977870, 2021). "Western blot analysis confirmed that combined treatment significantly reduced the expression levels of RAGE, p-STAT3, STAT3, p-AKT, and PCNA in tumor tissues compared to the PT or CQ monotherapy groups." (PMID 34771150, 2021). "STAT3-activating cytokines (e.g., IL6, IL10, VEGF) secreted by tumor cells promote abnormal dendritic cell differentiation and globally suppress dendritic cell maturation and activation." (PMID 34944848, 2021). "Additionally, since the secretion of certain cytokines by the activated STAT3 pathway could enhance the recruitment of monocytes and M2-type TAMs, CAFs can also be activated and thus progress to tumor cells and promote invading cells, as proven in squamous cell carcinomas." (PMID 34202411, 2021). "JAK2/STAT3, a critical signaling pathway in tumorigenesis, is mediated through EGFR signaling; STAT3 can act as a transcription factor for tumor progression." (PMID 33805840, 2021). "Together with the findings here we can draw the conclusion that IL-6 inhibits tumor growth by promoting the expression of E/P-selectin and ICAM-1 via JAK/STAT3 pathway and consequently facilitating T cells infiltration." (PMID 33390844, 2021). "IL-6/STAT3 signal axes elicit an immunosuppressive in tumor microenvironment, it is important to therapy HCC by blocking the IL-6/STAT3 signaling pathway." (PMID 34976809, 2021). "This study is to reveal the role of CREPT (cell cycle-related and elevated-expression protein in tumours, or RPRD1B) in promoting STAT3 transcriptional activity." (PMID 33531691, 2021). "In tumor bearing mice, axitinib suppressed MDSC accumulation through the inhibition of Stat3 activity and it was correlated with the reversal of T-cell suppression." (PMID 33854498, 2021). "Preclinical studies strongly suggest significant efficacy of drugs targeting GP130/JAK/STAT3 in the treatment of PDAC and that these molecules are effective chemosensitizers, possibly through simultaneous effect on tumor cells and TME." (PMID 34138876, 2021). "GW9662 treatment distinctly aggravated the decreased PPAR-γ expression levels and increased STAT3 and NF-κB phosphorylation in gastrocnemius muscles of LLC tumor–bearing mice as shown by the Western blot." (PMID 34093209, 2021). "Regarding other signaling pathways involved in GBM, STAT3 has been shown to be a molecular hub and its role in GBM tumor progression has been demonstrated." (PMID 34732244, 2021). "STAT3 is also abundantly activated in CRC and enhances cancer cell proliferation, tumor growth, invasion, and migration." (PMID 34440220, 2021). "Small molecule inhibitors that target the SH2 domain of STAT3 (e.g., C188-9, OPB-31121, OPB-51602, W2014-S, BBI-608) have demonstrated potent in vitro and in vivo anti-tumor activity in NSCLC models." (PMID 34944848, 2021). "Expression of a STAT3 dephosphorylase, CD45, has been identified in a group of MDSC, frequency of which in tumor site and peripheral blood is closely correlated with tumor stage and clinical outcomes." (PMID 34689842, 2021). "For instance, the STAT3 status, the FUNDC1 expression and the icaritin treatment implicate in regulating mitophagy and tumour immunity." (PMID 33605033, 2021). "More importantly, we confirmed that ICT1 protein levels had a positive correlation with the expression levels of BCL-2 in both xenografted tumor tissues and tissues derived from OS patients and that ICT1 regulated BCL-2 by controlling STAT3 phosphorylation." (PMID 33585660, 2021). "On the contrary, copper chelators can inhibit STAT3 and EGFR phosphorylation in cancer cells, to enhance PD-L1 degradation in vitro and in vivo, leading to strong anti-tumor activities." (PMID 34639141, 2021).
tumor (continued). "In tumor samples from patients with ICC, increased TAN and TAM levels were correlated with elevated p-STAT3 expression." (PMID 33692217, 2021). "miR-21 can activate NF-κB, STAT3 and bcl-2 signaling pathways by targeting PDCD4, thus reducing apoptosis in tumor cells." (PMID 34305614, 2021). "One other way is by increasing the expression of HIF-1α, as STAT3 is an upstream transcription factor for HIF-1α, in cancer cells and myeloid cells in the TME, which is critical for immunosuppression and tumor immune evasion." (PMID 34692527, 2021). "STAT3 is the most important downstream effector of OSM, which has been reported to be continuously activated in the GBM microenvironment and promote tumor invasion and progression." (PMID 34702277, 2021). "The results showed that the expression of STAT1, STAT2, STAT3, STAT5A, and STAT6 increased with increasing tumor grades." (PMID 34276757, 2021). "Signal transducer and activator of transcription 3 (STAT3) belongs to the STAT family and is a vital transcription factor involved in inflammation and tumour progression." (PMID 34707773, 2021). "Several marker genes, FOXP3, STAT3, PDCD1, TGFB1, IL10, HMGB1, which are significantly related to the tumor microenvironment induced by radiation, had significant functional differences in the distribution of CD8+T cells clusters." (PMID 33968889, 2021). "Of note, alternatively activated macrophages and MDSCs are a major source of STAT3-activating cytokines such as IL6 and IL11, which form a paracrine loop to perpetuate a tumor-reactive microenvironment by acting on cancer cells." (PMID 34944848, 2021). "Collectively, our data suggested that DNM3 suppresses LC tumor growth and migration by interacting with GBR2, which subsequently leads to the dissociation of the c-MET and STAT3 complex." (PMID 34490234, 2021). "STAT3 is constitutively hyperactivated in DFT1, involved in the down-regulation of MHC-I in this tumour, and here we have demonstrated that DFT2 cells express similar levels of STAT3 to DFT1, despite still expressing MHC-I." (PMID 34780568, 2021). "Due to CTLA4 upregulation on tumor–infiltrating CD8+ T cells, a CTLA4‐targeting aptamer STAT3 siRNA chimera was created that triggers CD8+ T cell reactivation in the tumor microenvironment." (PMID 34532286, 2021). "The Stat3 and p38 MAPK signaling pathways play important roles in multiple biological activities of tumor cells such as proliferation, cell cycle, and autophagy." (PMID 34733155, 2021). "Increased IL17 levels correlate with tumor recurrence, metastasis, and poor survival in pre-clinical models and NSCLC patients by enhancing VEGF-mediated angiogenesis in a STAT3-dependent manner." (PMID 34944848, 2021). "A previous study identified tumor cell-intrinsic TGFβ and IL-1/JAK/STAT3 signaling as the major pathways responsible for myCAF and iCAF formation." (PMID 34035226, 2021). "In our previous studies, we have developed and evaluated several small molecule STAT3 inhibitors, including LLL12, which blocks STAT3 phosphorylation and exhibits potent tumor growth-suppressive activity in cancer." (PMID 33753770, 2021). "Authors reported that JAK2-specific inhibitors had been shown in reducing tumor growth in TNBC cells, but JAK1/STAT3 inhibitor had little effect, sometimes counteracting the JAK2 specific inhibition on TNBC in an in vivo model." (PMID 35010954, 2021). "Accelerated tumor growth was accompanied by metabolic perturbations in CD8+ TILs that impaired their anti-tumor activity, including elevated STAT3 signaling, increased Cpt1b expression, and increased fatty acid oxidation at the expense of glycolysis." (PMID 34421889, 2021). "In GBM, interactions between tumor cells, reactive astrocytes, and microglia lead to high levels of IL-10 and TGF-β, which promotes a positive feedback loop of STAT3 signaling." (PMID 33498872, 2021).
tumor (continued). "Hence, we mainly focused on STAT3, a well‐known aberrantly activated oncogene in many human cancers, which relays cytokine receptor‐generated signals into the nucleus to stimulate cell proliferation, prevent apoptosis, promote angiogenesis and facilitate tumor immune evasion." (PMID 33176070, 2021). "In NB, it was shown that these CAF-like MSCs as well as normal BM-MSCs enhance tumor cell proliferation and survival in vitro and stimulate tumor engraftment and growth in vivo through the JAK2/STAT3 and MEK/ERK1/2 pathways in NB cells." (PMID 33287630, 2021). "In BLCA, miR-153 anti-tumor activity was mediated by targeting IDO1, further inactivating IL6/STAT3/VEGF signaling pathway." (PMID 33672684, 2021). "We identify a Stat3/HIF-1α-mediated axis, through which IL-6 executes an anti-tumor role to induce CD40 expression in Mφs." (PMID 34103524, 2021). "We know that MSCs are highly prone to tumour stroma and can promote MDR by increasing the expression of multi-drug resistance genes or by paracrine pathways (STAT3, IL-6, IL-8, etc.)." (PMID 33541299, 2021). "In conclusion, our data have confirmed the tumor suppressor function of DNM3 in LC and that it is mediated through suppression of the STAT3 signaling pathway." (PMID 34490234, 2021). "In vivo, the treatment with OV, alone or in combination with cisplatin, was able to reduce the oncogenicity of tumorspheres, also decreasing the content of PI3K, STAT3, mTOR, TGF-β1, and miR-21-5p in CSC-EVs of tumor samples explanted from OV-treated mice." (PMID 34638913, 2021). "Within the TME, DCA treatment reduces lactate release, STAT3 activation, IDO1 over-expression and MDSC infiltration, leading to enhanced anti-tumor immune response and prolonged survival of mice." (PMID 34696286, 2021). "The paradoxical increase in tumor migration by GMZ has been described by Xu at al. and is related to the activation of EGFR and STAT3 pathways by this drug." (PMID 34201986, 2021). "RPS6-KD suppressed the tumor-sphere formation of GBM cells through the inhibition of p-JAK2 and p-STAT3 and concomitantly downregulated the stemness-related proteins Nestin and SOX2." (PMID 35008473, 2021). "The Janus kinase 2 (JAK2)/signal transducer and activator of transcription 3 (STAT3) axis has been demonstrated to play a crucial role in the progression of HCC and is involved in the process of tumor metastasis." (PMID 34113574, 2021). "In tumor tissue cells, owing to various factors, the activation of signal transducer and activator of transcription 3 (STAT3) appears to be in a persistently and abnormally high expression state, which leads to abnormal proliferation of malignant tumor cells." (PMID 34789307, 2021). "STAT3 activation attenuated STING-induced anti-tumor immunity, while the STING agonist induced an immune response that in turn restricted STAT3 activation in tumor cells." (PMID 34299262, 2021). "As aberrant IL‐6–JAK–STAT3 signaling is an important mechanism for cancer initiation, development, and progression, S1P/S1PR1 signaling accelerates tumor growth and metastasis via an IL‐6/JAK2‐mediated persistent activation of STAT3." (PMID 34289244, 2021). "Genetic depletion of CD36 or inhibition of STAT3/5 restricted oxidative metabolism and immunosuppressive function in MDSCs, resulting in CD8+ T cell-dependent tumor delay due to reduced ARG1 and iNOS." (PMID 34742349, 2021). "Exosomal HSP70 induces STAT3 phosphorylation and increases secretion of IL-6 and vascular endothelial growth factor (VEGF) in MDSCs, thus promoting tumor growth." (PMID 34917098, 2021). "This study found that LNT caused a significant increase in miR-216a-5p expression levels in tumor cells; decreased related protein expression in the JAK2/STAT3 pathway." (PMID 34900727, 2021). "This is relevant to studying STAT3 biology given its pertinent roles in CAF function and CAF-tumor cell crosstalk as previously discussed." (PMID 34858425, 2021).